IFNG (interferon gamma)
Diseases named in the same sentence as IFNG in open-access papers (continued):
Sharing a sentence is not in itself a finding about the gene and the disease.
influenza (continued). "Transcriptomic analyses revealed that compared to influenza-infected mice, SARS-CoV-2-infected mice had reduced interferon-gamma/alpha responses at 4 DPI and failed to induce keratin 5 (Krt5) at 6 DPI in lung, a marker of nascent pulmonary progenitor cells." (PMID 38092883, 2023). "PBMCs from pneumococcal colonised (n = 10) and non-colonised (n = 8) adults stimulated ex vivo with influenza antigen elicited similar frequencies of TNF+, IL-17A+ and IFNγ+ CD4+ memory T-cells." (PMID 23555269, 2013). "Although the PAR2-induced bactericidal activity is not enhanced in the presence of IFNγ in neutrophils, PAR2 agonist and IFNγ synergize boosting anti-influenza effects in human monocytes." (PMID 24171176, 2013). "In addition, NK cells may also be a contributor: IFNG transcript was increased more in COVR-M than HC-M and COVR-F on day 1 after influenza vaccination in CD16lo NK cells (p<0.05; data not shown)." (PMID 35233581, 2022). "In addition, a study that observed CXCR3+ cTfh to positively correlate with antibody responses after influenza vaccination also showed that CXCR3+ Tfh that were localized to tonsillar GCs, expressed Fas-L, secreted IFNγ, lacked CD154 expression, and suppressed the activity of GC B cells." (PMID 30090099, 2018). "However, not all influenza-specific CD4 T cells express both IL-2 and IFNγ." (PMID 24788814, 2014).
asthma (625 papers, 2005 to 2026). "This is important because both a Th1 phenotype and IFNγ—the main cytokine produced by Th1 cells—are implicated in the inhibition of the allergic march and, therefore, asthma." (PMID 41010514, 2025). "In patients, pulmonary IFNγ responses were enhanced in severe asthma associated with neutrophilic inflammation, and serum IFNγ levels correlated with airway responsiveness." (PMID 40016948, 2025). "To determine the effects of IFNγ on asthma phenotypes, we measured the expression of genes associated with inflammation and Th2 responses." (PMID 38081868, 2023). "To determine the effects of IL-31 on the expression of asthma-associated genes, we quantified the expression of genes associated with inflammation (IFNγ, TNF-α, IL-6, and IL-17) and Th2 responses (IL-4, IL-13, ARG1, MUC4, and MUC5AC)." (PMID 38081868, 2023). "In contrast, airways of type 2-low asthma demonstrate neutrophilic and pauci-granulocytic airway infiltrates that are associated with cytokines such as interferon gamma (IFN-γ), IL-6 and IL-17." (PMID 37893223, 2023). "Despite the reduced expression of several Th2-associated asthma genes, IFNγ treatment induced AHR, inflammation, and goblet cell hyperplasia." (PMID 38081868, 2023). "In a candidate-gene association study in individuals of European descent, genotype-by-sex interaction at interferon-gamma (IFNG) was shown to affect the risk for childhood asthma." (PMID 34834492, 2021). "Where asthma and the common cold are directly linked to Interferon-gamma (IFNg), IL-8, IL-2 and IL-5, diarrhea is linked to IL-18." (PMID 32746922, 2020). "Again, BioPM induced cytokine production in a concentration-dependent manner by PBMCs from patients during loss of asthma control (with the exception of IFNγ and TNFα production induced by BioPM from the goat farm)." (PMID 32620109, 2020). "We observed an excess of genes jointly controlled by asthma- and hypertension-associated eQTLs in modules enriched with genes involved in interferon-gamma signaling and chromatin assembly." (PMID 31705029, 2019). "Cytokines such as interferon gamma (IFN-γ) that induce the release of Th1 cells are associated with the severity of asthma." (PMID 31790411, 2019). "Further, IL-17 and IFNγ production were associated with asthma severity in some steroid-resistant patients." (PMID 30105031, 2018). "Treg cells that lack FoxO1 upregulate expression of the pro-inflammatory cytokine interferon γ (IFNγ), the production of which is linked to severe, glucocorticoid-resistant asthma in humans." (PMID 28267764, 2017). "Increasing levels of IFNγ and LPS (endotoxin) are directly associated with severity of asthma, and investigations with these factors demonstrate that they drive critical pathogenic mechanisms linked to exacerbations." (PMID 27657907, 2016). "Emerging evidence suggests that environmental triggers for allergic asthma can alter DNA methylation in the IFNγ gene promoter and thereby modify asthma risk." (PMID 24891923, 2014). "On the other hand, interferon-γ (IFNγ), a Th1-associated cytokine, was reported to reduce the symptoms of asthma in asthmatic patients." (PMID 23781124, 2013). "Our present findings indicate that maternal exposure to PAHs is associated with the DNA methylation status of a known asthma gene, IFNγ." (PMID 22562770, 2012). "Epigenetic changes have been shown to affect FOXP3 and IFNγ expression and mutations and/or deficiencies in FOXP3 or IFNγ can result in development in autoimmune disease, infections or asthma." (PMID 23226205, 2012). "Recently, it has been shown that prenatal maternal exposure to Acinetobacter lwoffii F78 prevented the development of asthma in the progeny which was associated with changes in H4 acetylation at the IFNG promoter." (PMID 22792257, 2012). "In a recent study, prenatal administration of mice with Acinetobacter lwoffii F78 prevented asthma in the offspring in an IFNγ-dependent manner and was associated with histone H4 acetylation at the IFNG promoter." (PMID 23724235, 2011).
asthma (continued). "In addition, leptin—another major adipokine—has been shown to stimulate the production of proinflammatory cytokines such as TNF-α, IL-6, and interferon gamma (IFN-γ), all of which are implicated in the pathology of asthma." (PMID 40653199, 2025). "Moreover, we recently showed that uncontrolled Tnfaip3‐deficient cDC1 activity suppressed Tc2 cell formation via IFNγ in a HDM‐driven asthma model." (PMID 40016948, 2025). "Other studies, however, have shown a strong correlation between maternal and cord blood IFNγ concentrations and that detectable cord blood concentrations of IFNγ are associated with a lower risk of asthma and atopy at age 6 years, and detectable cord blood TNF‐α with a lower risk of atopy." (PMID 40714954, 2025). "The IFNG gene is located on chromosome 12q14, with several SNPs in this gene reported and associated with diseases such as aplastic anemia, infectious hepatitis, systemic lupus erythematosus, and asthma." (PMID 39066175, 2024). "Multiple cytokines, including IFNγ, IL-4, and IL-13 are associated with asthma; however, the mechanisms underlying the effects of these cytokines remain unclear." (PMID 38081868, 2023). "Enhanced IFNγ production by PBMCs was also seen for asthmatic children, but despite similar seroprevalence not in non-asthmatic children, in an in vitro response to Chlamydia pneumoniae, which has been associated with asthma exacerbations." (PMID 32620109, 2020). "PBMCs from asthma patients during loss of control showed enhanced IFNγ levels compared to stable disease after exposure to 1 μg/ml BioPM collected from the pig farm, but no other differences in BioPM-induced cytokine production were found between the two groups." (PMID 32620109, 2020). "Besides variation in potency, it became clear that BioPM from pig farms uniquely induced IFNγ production by PBMCs collected during loss of asthma control." (PMID 32620109, 2020). "However, PBMCs obtained during loss of asthma control demonstrated an enhanced IFNγ response upon exposure to BioPM from the pig farm, which was paralleled by oxidative stress." (PMID 32620109, 2020). "Interestingly, PBMCs from patients during loss of asthma control showed enhanced IFNγ and oxidative stress responses upon stimulation with BioPM from the pig farm, indicating increased susceptibility to this particular livestock." (PMID 32620109, 2020). "Furthermore, PBMCs obtained during loss of asthma control that were exposed to BioPM from pig farms showed enhanced IFNγ release as well as decreased oxidative stress levels upon pre-treatment with N-acetylcysteine (NAC) compared to stable disease." (PMID 32620109, 2020). "In addition to evaluating the relationship between nutritional intake and asthma health, a potential epigenetic mechanism was examined by determining if global methylation or IFNγ promoter methylation was associated with nutritional intake." (PMID 28261276, 2017). "Kumar et al13 first described a significant association of an intronic SNP of the IFNG gene with asthma and identified the association of rs1861494 A/G polymorphism with asthma, which may control the IFN-γ levels and thus modulate asthma pathogenesis." (PMID 27124053, 2016). "Although increasing levels of IFNγ and LPS (endotoxin) are directly associated with severity of asthma, and investigations with these factors demonstrate that they drive critical pathogenic mechanisms linked to exacerbations, they do not replicate the complexity of infection." (PMID 27657907, 2016). "Furthermore, that serum interferon gamma was associated with asthma-related impairment in our study expands on a previous study that found significant association between airway responsiveness and serum interferon gamma." (PMID 23468925, 2013). "Moreover, IFNγ-producing Th1 cells have been implicated in the development of severe macrophage-dependent, steroid-resistant asthma." (PMID 23291461, 2013).
asthma (continued). "We hypothesized that functional impairment of Treg and Teff cells are due to epigenetic and molecular modifications in FOXP3 and IFNγ that are mechanistically linked to outcomes of asthma." (PMID 23226205, 2012). "Teff phenotype and function also appear to be under regulation of epigenetic modifications as methylation of key CpG sites within the IFNγ locus leads to decreased IFNγ expression within Teff, and skews Teff towards a T helper (Th) type 2 phenotype associated with asthma." (PMID 23226205, 2012). "Collectively, these observations suggest that IFNγ, previously thought to be protective in asthma, could be pathogenic in a specific population of asthma (T2-low, chronic, severe) and COPD (with acute exacerbations) patients and can contribute to the poor GC responsiveness seen in these patients." (PMID 36012240, 2022). "In addition, the STAT6 SNP rs324015 was associated with reduced SEA-specific IFNγ when comparing genotypes, and this SNP has been previously associated with reduced asthma risk and reduced IgE, thereby indicating that this polymorphism results in a dampening of TH2 responses." (PMID 35759449, 2022). "Interestingly, IFNG is an inflammatory cytokine implicated in the pathophysiology of asthma." (PMID 27445529, 2016). "Therefore it can be postulated that hormone-related changes with puberty may alter DNA methylation and histone modification patterns in asthma genes like IFNγ, thus increasing or decreasing the risk of diseases like asthma." (PMID 24891923, 2014). "In summary, we found that significant asthma-related respiratory impairment persists in 40% of cedar asthmatic even long since (on average, 17 years) removal from exposure and is associated with a classical marker of circulating inflammation (interferon-gamma)." (PMID 23468925, 2013). "Concurrently, TSG enhanced Th1 responses, indicated by increased IFNγ levels, suggesting rebalancing of the Th1/Th2 immune response, which is crucial in asthma management." (PMID 40598285, 2025). "Our recent finding of increased levels of Tc cells displaying a hybrid Tc1/Tc2 phenotype (i.e., producing both IFNγ and type‐2 cytokines) in exacerbating asthma patients and in mice with type 2‐high airway inflammation is in line with Tc1‐to‐Tc2 plasticity." (PMID 40016948, 2025). "A systems pharmacology approach has identified the capacity of baicalin to target 48 asthma-related genes such as IFNγ, IL4, IL5, IL10, IL13, and TNFα and signaling pathways, reinforcing its polypharmacological properties." (PMID 40598285, 2025). "IL-4 is a key cytokine in the induction of Type 2 helper T cells (Th2) that mediate allergy, asthma, and wound repair, and in addition, acts as an anti-inflammatory cytokine that antagonizes Type 1 (IFNγ) immune responses." (PMID 40738263, 2025). "Here we provide compelling evidence that the Tc cell compartment in asthma undergoes substantial phenotypic skewing, resulting in a functional shift away from type-1 (e.g., IFNγ) and towards type-2 (e.g., IL-5, IL-9) cytokine production." (PMID 37612281, 2023). "Asthma endotypes with increased type 1 or 17 inflammation have increased neutrophil infiltration and are mediated by effector cytokines, namely IFNγ and IL-17A, respectively." (PMID 37047327, 2023). "Increased frequencies of Tc cells producing both IFNγ and type-2 cytokines in patients suggest that asthma coincides with elevated Tc1-to-Tc2 cell skewing, which occurs in a concerted manner across both T-cell compartments." (PMID 37612281, 2023). "This elderly asthma cohort also had increased IFNγ and IL-17 levels in sputum, while levels of type 2 markers, IgE and FeNO, were lower than those in younger asthma patients." (PMID 37047327, 2023). "Upon exacerbating, asthma patients showed significantly decreased frequencies of IFNγ+ and simultaneously increased frequencies of IL-4+, IL-5+, and IL-9+ Tc and Th cells." (PMID 37612281, 2023).
asthma (continued). "IFNγ expression is heightened in patients with a severe asthma phenotype, and administration of recombinant IFNγ to mice with induce AHR that is steroid-resistant." (PMID 37377967, 2023). "Mouse models of asthma recapitulate the human disease by showing extensive type-2 skewing of lung Tc cells, which is controlled by conventional type-1 dendritic cells and IFNγ." (PMID 37612281, 2023). "When comparing the frequencyof the IFNG rs2069705 genotypes, the homozygous TT wasshown to be significantly higher in the controlled asthma groupcompared to the control group ( p < 0.05)." (PMID 37465198, 2023). "While working, we have also found that the AA genotypeof IL17A rs2275913, the TT genotype of IFNG rs2069705,and the A allele of TNFA rs1800629 were associated withmild asthma, and the TT genotype of IFNG rs2069705 – withcontrolled asthma." (PMID 37465198, 2023). "Here we show increased circulating Tc2 cell abundance in severe asthma patients, reaching peak levels during exacerbations and likely emerging from canonical IFNγ+ Tc cells through plasticity." (PMID 37612281, 2023). "To determine the effects of IFNγ on asthma phenotypes, we treated wild-type mice with saline or IFNγ and measured the changes in AHR, inflammation, and goblet cell hyperplasia." (PMID 38081868, 2023). "The AA genotype of IL17A rs2275913, the TT genotype of IFNG rs2069705 and allelic A variants of TNFA rs1800629 are associated with mild asthma, and the TT genotype of IFNG rs2069705 is additionally associated with controlled asthma." (PMID 37465198, 2023). "Patients with severe asthma who respond poorly to corticosteroid therapy have been shown to have dominant Th1 responses, including elevated IFNγ in their lungs." (PMID 38081868, 2023). "Recent studies show the presence of type 1 and 17 inflammation, characterized by increased neutrophils and IL-17A and IFNγ levels, are more common in older individuals with asthma." (PMID 37047327, 2023). "Together, these novel studies show the combined effects of TNFα and IFNγ on pediatric ASM and implicate Th1-associated cytokines in promoting ASM inflammation and hypercontractility in severe asthma." (PMID 35578269, 2022). "Asthma mice can be regulated by N. officinalis affecting the secretion of cytokines, such as interferon gamma (IFN-γ), interleukin (IL) -10, IL-5, IL-4, and IL-2, and the infiltration of inflammatory cells in the airway." (PMID 36539909, 2022). "Microarray data of cells from BAL of patients with asthma also identifies a IFNγ high subgroup of asthmatics." (PMID 36237537, 2022). "Building upon these studies, we performed RNA-seq to examine the individual and combined effects of TNFα and IFNγ on gene expression in the context of corticosteroid insensitivity in pediatric asthma." (PMID 35578269, 2022). "TNFα/IFNγ was found to augment the expression of several genes that contribute to airway inflammation, hypercontractility and remodeling in asthma while also reducing expression of key anti-inflammatory genes, such as KLF15." (PMID 35578269, 2022). "Amongst these cytokines, the involvement of TNFα and IFNγ in GCI in asthma received significant attention over the past decades." (PMID 36012240, 2022). "Multiple studies have reported increased levels of IFNγ, a Th1 cytokine, and Th1 lymphocyte infiltration in lung-derived samples from adults with severe asthma." (PMID 35578269, 2022). "IFNγ also induces pro-inflammatory responses in ASM and has been implicated in mediating airway hyperresponsiveness in asthma." (PMID 35578269, 2022). "Children with asthma have lower levels of interferon-gamma and consequently reduced angiotensin-converting enzyme 2 (ACE-2) gene expression in airway epithelium, which act as the entry point of SARS-CoV-2 into the human body." (PMID 34845526, 2022). "Murine asthma models have shown that exposure to PM increased neutrophil infiltration by increasing tumor necrosis factor alpha and interferon gamma excretion." (PMID 34445977, 2021).